Y_RNA (Y RNA )
Gene: Miscellaneous RNA gene on chromosome 18 (2,621,090 to 2,621,201, forward strand). Ensembl gene ENSG00000202224.
Homologues: Orthologues: chimpanzee Y_RNA (99% identical), macaque Y_RNA (93% identical). Paralogues in human: Y_RNA (84% identical), RNY1P5 (83% identical), Y_RNA (83% identical), Y_RNA (82% identical), Y_RNA (81% identical), Y_RNA (80% identical), RNY1P1 (79% identical), Y_RNA (79% identical), Y_RNA (78% identical), Y_RNA (77% identical), RNY1P6 (76% identical), Y_RNA (76% identical), and 94 more.